MCC (MCC regulator of Wnt signaling pathway)
Description:
Candidate for the putative colorectal tumor suppressor gene located at 5q21. Suppresses cell proliferation and the Wnt/b-catenin pathway in colorectal cancer cells. Inhibits DNA binding of b-catenin/TCF/LEF transcription factors. Involved in cell migration independently of RAC1, CDC42 and p21-activated kinase (PAK) activation. Represses the beta-catenin pathway (canonical Wnt signaling pathway) in a CCAR2-dependent manner by sequestering CCAR2 to the cytoplasm, thereby impairing its ability to inhibit SIRT1 which is involved in the deacetylation and negative regulation of beta-catenin (CTNB1) transcriptional activity.
Synonyms: MCC1
Tractability: Antibody: its Gene Ontology location is reachable by antibodies, with high confidence; UniProt places it where antibodies can reach, with medium confidence. PROTAC: ubiquitination databases record sites on it; its protein half-life has been measured.
Gene: Protein-coding gene on chromosome 5 (113,022,106 to 113,488,823, reverse strand). Ensembl gene ENSG00000171444.
Subcellular location: Cell membrane; Cell projection, lamellipodium; Nucleus; Cytoplasm
Subcellular location (Human Protein Atlas): Nucleoplasm; Cytosol
Gene Ontology:
Molecular function: protein binding; signaling receptor activity
Biological process: establishment of protein localization; negative regulation of canonical Wnt signaling pathway; negative regulation of epithelial cell migration; negative regulation of epithelial cell proliferation; signal transduction
Cellular component: cytoplasm; cytosol; nucleoplasm; nucleus; plasma membrane; lamellipodium
Genetic constraint (gnomAD): Loss-of-function variants: 84 observed, 109.75 expected, observed/expected ratio (o/e) 0.77, 90% interval 0.64 to 0.92. The upper end of that interval is the gene's LOEUF score, 0.92, which puts it in group 3 of 6, group 1 being the genes least tolerant of losing a copy. Missense variants: 1,477 observed, 1,303.8 expected, observed/expected ratio (o/e) 1.13, 90% interval 1.09 to 1.18. Synonymous variants: 565 observed, 506.67 expected, observed/expected ratio (o/e) 1.12, 90% interval 1.04 to 1.2.
Homologues: Orthologues: chimpanzee MCC (99% identical), macaque MCC (99% identical), pig MCC (96% identical), guinea pig MCC (95% identical), mouse Mcc (93% identical), rat Mcc (93% identical), tropical clawed frog mcc (89% identical), dog MCC (78% identical), zebrafish mcc (77% identical), rabbit MCC (68% identical), Drosophila melanogaster CG34404 (17% identical). Paralogues in human: USHBP1 (19% identical).
Diseases named in the same sentence as MCC in open-access papers:
MCC is named in the same sentence as 60 diseases in open-access papers, as found by Europe PMC text mining. Sharing a sentence is not in itself a finding about the gene and the disease. The quoted sentences say what the papers report.
colorectal cancer (21 papers, 1994 to 2025). A primary or metastatic malignant neoplasm that affects the colon or rectum. "Among genes with defective expression, it is also noteworthy to mention MCC (Mutated In Colorectal Cancers), which is specifically down-regulated in STAT3-mutated cases." (PMID 40721648, 2025). "The mutated in colorectal cancer (MCC) gene, located on the long arm of chromosome 5 (5q21), encodes a multifunctional protein also known as MCC." (PMID 39439956, 2024). "MCC/MCC1 (“mutated in colorectal cancer”) plays a significant role in colorectal cancer progression." (PMID 37569317, 2023). "The gene MCC Regulator of Wnt Signaling pathway, MCC, is a tumor suppressor gene and somatic mutations have been detected in colorectal cancer." (PMID 36349425, 2023). "We also show that in addition to promoter hypermethylation, MCC silencing is associated with hypomethylation of distant gene regions in a small subset of colorectal cancers." (PMID 35740525, 2022). "As a result, epidermal growth factor (EGF), MAP2K2, MCC (mutated in colorectal cancer), and NRAS (neuroblastoma RAS viral oncogene homolog) were determined as remarkably prognostic-related genes." (PMID 33553243, 2020). "It is noteworthy that MCC did not only function as an independent tumor suppressor in the majority of colorectal cancers, but also functioned as a susceptibility gene in HSCR." (PMID 29695640, 2018). "Mutations and loss of heterozygosity (LOH) in the MCC gene have previously been found to be relevant to colorectal cancer." (PMID 27226254, 2016). "In A549IR cells, down-regulation of the Wnt signaling pathway might be associated with upregulation of the MCC gene which can suppress cell proliferation and the Wnt/β-catenin pathway in colorectal cancer cells." (PMID 36769365, 2023). "MCC methylation is also associated with more invasive colorectal cancers." (PMID 34298744, 2021). "By doing so, we aimed to confirm the hypothesis that the MCC gene may be involved in the genetically reduced susceptibility to colorectal cancer in patients with schizophrenia." (PMID 27226254, 2016). "Paradoxically, in contrary to the up-regulation of MCC in B cell neoplasms, the MCC gene is frequently deleted, mutated, or silenced in other human cancers, including colorectal cancer, lung cancer, gastric carcinoma, esophageal cancer, and hepatocellular carcinoma." (PMID 25200342, 2014). "Besides the bona fide tumor suppressor APC, 5q22.2 also encodes the gene MCC (mutated in colorectal cancer)." (PMID 20707908, 2010). "MCC, which located on chromosome 5q21 and encoded a protein that comprised 829 amino acids, is a candidate colorectal cancer suppressor gene that is reported to negatively modulate cell growth and differentiation and cell cycle and could suppress Wnt/β-catenin signal transduction." (PMID 33553243, 2020). "Functional studies in colorectal cancer revealed that MCC is a candidate tumor suppressor that negatively regulates cell cycle progression, cell proliferation and migration, and is required for DNA damage response." (PMID 40721648, 2025). "These complementary experimental approaches will not only strengthen the evidence supporting the role of MCC in Treg function, but also provide valuable insights for potential therapeutic interventions targeting MCC in colorectal cancer." (PMID 37569317, 2023). "The ‘Mutated in Colorectal Cancer’ (MCC) gene was discovered due to its close proximity to the APC gene on chromosome 5, but it has APC-independent roles in colorectal cancer." (PMID 35740525, 2022). "Differential methylation of MCC is potentially a valuable biomarker to identify colorectal cancers suitable for irinotecan therapy, possibly in combination with PARP inhibitors." (PMID 35740525, 2022). "While MCC promoter methylation is found in almost all CIMP-H colorectal cancers, we set out to understand how this relates to the level of methylation, using the HM27 array data available for the TCGA 2012 cohort." (PMID 35740525, 2022).
colorectal cancer (continued). "MSI-H was also strongly associated with CIMP-H in sporadic colorectal cancers, as expected, and with concurrent CDKN2A/MCC methylation." (PMID 34298744, 2021). "MCC is a tumor suppressor in different types of cancers, including hepatocellular carcinoma, colorectal cancer (CRC) and acute myeloid leukemia." (PMID 29695640, 2018). "The four genes linked to colorectal cancer (NRAS, PIK3CA, MCC, APC) all show lower methylation in the AA/YRI groups." (PMID 25742137, 2015). "Our results indicate that in sharp contrast to its tumor suppressive role in colorectal cancer, MCC functions as an oncogene in B cells." (PMID 25200342, 2014). "We confirmed the recently observed associations between DNA hypermethylation of BMP3 and MCC with CIMP+ and BRAFV600E in colorectal cancer." (PMID 20027224, 2009). "Thus, differential methylation of MCC is potentially a valuable biomarker to identify colorectal cancers suitable for irinotecan therapy, possibly in combination with PARP inhibitors." (PMID 35740525, 2022). "MCC is also an intriguing HCC candidate gene because of its genomic proximity to APC, a major tumor suppressor mutated in familial adenomatous polyposis preceding colorectal cancer." (PMID 23540693, 2013). "OMIM disease analysis also revealed two genes—MCC and PDGFRL—with an impact on the colorectal cancer process." (PMID 37762215, 2023). "Our analysis of the TCGA cohorts shows that MCC is highly methylated in all CIMP-H and half of CIMP-L colorectal cancers." (PMID 35740525, 2022). "Further research has revealed the role played by MCC in inhibiting cell cycle progression, not only in NIH3T3 fibroblasts but also in colorectal cancer (CRC), highlighting the significance of MCC in regulating cell growth and its potential effects on cancer development." (PMID 39439956, 2024). "In addition to the five CIMP markers, genes that show concordant methylation in colorectal carcinoma include CDKN2A (p16) and MCC." (PMID 34298744, 2021). "Therefore, the aim of this study was to determine the association of EMAST with (i) clinicopathological features in colorectal carcinoma, (ii) MSI, (iii) CIMP and (iv) methylation of selected genes MSH3, MCC and CDKN2A (p16)." (PMID 34298744, 2021). "Taken together, the genomic data from the two TCGA colorectal cancer cohorts suggest that MCC is silenced by CpG island hypermethylation in CIMP-H colon cancers, while low MCC expression is associated with other factors in non-CIMP cancers, such as shore/shelf hypomethylation and gene deletions." (PMID 35740525, 2022).
glioma (4 papers, 2015 to 2024). A benign or malignant brain and spinal cord tumor that arises from glial cells (astrocytes, oligodendrocytes, ependymal cells). "Additionally, analysis of CGGA data revealed that MCC methylation significantly decreases with increasing WHO glioma grade." (PMID 39439956, 2024). "Supporting these findings, analyses of The Cancer Genome Atlas (TCGA), Chinese Glioma Genome Atlas (CGGA), and Genotype-Tissue Expression (GTEx) databases confirmed higher MCC expression in glioblastoma tumors than in normal brain tissue." (PMID 39439956, 2024).
colon cancer (3 papers, 2014 to 2022). "MCC deficiency increases DNA breaks in response to irinotecan in colon cancer cells, as well as in response to free radical generation by H2O2 in mouse embryo fibroblasts." (PMID 35740525, 2022). "We also examined HCT116 colon cancer cells that were beta-catenin-mutated and CIMP-positive but had endogenous MCC expression." (PMID 35740525, 2022). "Endogenous MCC was immunoprecipitated from sub-confluent human colon cancer cell line SW480." (PMID 25997006, 2015). "In conclusion, reduced MCC expression sensitizes mouse embryo fibroblast and HCT116 colon cancer cells to SN38/irinotecan-induced cell death, and PARP inhibitor Olaparib augments this effect." (PMID 35740525, 2022). "Confocal microscopy also showed that endogenous MCC partially co-localizes with endogenous SHANK3 at the cell membrane of SW480 and HCT116 colon cancer cells." (PMID 25997006, 2015). "The R414C mutation was first identified by Nishisho and colleagues in 1991 who were originally attempting to analyze four possible genes (MCC, TB2, SRP, and APC) which were involved in this inherited form of colon cancer in a cohort of ninety FAP patients." (PMID 24790607, 2014).
colorectal tumor (3 papers, 2010 to 2021). "MCC regulator of WNT signaling pathway (MCC) is a potential colorectal tumor suppressor gene and may negatively regulate cell cycle progression." (PMID 34926519, 2021). "Importantly, our analyses revealed that, while known CRC driver genes APC and SMAD4 were disrupted in both human colorectal tumors and tumors from ApcMin/+ mice, the questionable MCC gene was disrupted in human tumors but appeared to be intact in mouse tumors." (PMID 20707908, 2010). "Our results indicate that MCC is unlikely a player in early colorectal tumorigenesis, and we hypothesize that its disruption in human colorectal tumors is most likely a mere result of its close proximity to APC in the human genome." (PMID 20707908, 2010). "For instance, in addition to the induction of the MCC protein, β-catenin/TCF4-induced SRSF3 expression decreased Rac1b expression in colorectal tumor cells by increasing skipping of alternative exon 3b." (PMID 33072610, 2020).
gastric cancer (3 papers, 1996 to 2021). A primary or metastatic malignant neoplasm involving the stomach. "Furthermore, loss-of-function mutations, LOH, or decreased expression of the MCC gene are also detected in a number of other human cancers, including lung cancer, gastric carcinoma, esophageal cancer, and hepatocellular carcinoma." (PMID 25200342, 2014). "We thus find that alteration of the APC and MCC genes are infrequent in gastric cancers from the British population." (PMID 8855982, 1996).
adenoma (2 papers, 2010 to 2023). A neoplasm arising from the epithelium. "At the core of the classical pathway of CRC development (‘adenoma–carcinoma sequence’) are genetic alterations of several suppressor genes such as APC, responsible for the development of FAP, and a gene known as colorectal mutant cancer protein (MCC)." (PMID 37760539, 2023).
B-cell neoplasm (2 papers, 2014 to 2015). A group of heterogeneous lymphoid tumors generally expressing one or more B-cell antigens or representing malignant transformations of B-lymphocytes. "Our study also discovered a number of candidate therapeutic targets for the treatment of B cell neoplasms, including NF-κB2, PKCδ, MCC, PARP1, and PHB2." (PMID 25960828, 2015). "Our unexpected finding that MCC is strikingly up-regulated in TRAF3−/− mouse B lymphomas prompted us to further investigate the expression and function of MCC in B cell neoplasms." (PMID 25960828, 2015). "Our unexpected finding that MCC was strikingly up-regulated in TRAF3−/− mouse B lymphomas prompted us to further examine MCC expression in human B cell neoplasms." (PMID 25200342, 2014). "Our knockdown studies also suggest that MCC could serve as a therapeutic target in B cell neoplasms." (PMID 25960828, 2015). "Since our new proteomic data identified PARP1 and PHB2/PHB1 as two signaling hubs of the novel oncoprotein MCC in human MM cells, we are currently testing the therapeutic efficacy of PARP1 inhibitors and PHB ligands in B cell neoplasms with TRAF3 inactivation or aberrant MCC expression." (PMID 25960828, 2015). "Given the preclinical evidence that both PARP1 and PHB2/PHB1 are excellent therapeutic targets in human cancers, our findings also implicate potential applications of PARP inhibitors and PHB ligands in the treatment of B cell neoplasms involving TRAF3 inactivation or aberrant MCC expression." (PMID 25960828, 2015).
esophageal cancer (2 papers, 2014 to 2019). A primary or metastatic malignant neoplasm involving the esophagus. "Several reports have described high rates of loss of heterozygosity at MCC in esophageal cancer." (PMID 31834866, 2019). "A prognostic methylation marker (cg18276155) for EAC was located at a classic tumor suppressor gene of esophageal cancer, MCC gene." (PMID 31834866, 2019). "Among our methylation signatures, some genes have been reported in the onset and progression of BE and esophageal cancer or the prognosis of esophageal cancer, such as TRIM15, TACC3, SHANK2, and MCC." (PMID 31834866, 2019).
Familial adenomatous polyposis (2 papers, 2013 to 2014). Familial adenomatous polyposis (FAP) is characterized by the development of hundreds to thousands of adenomas in the rectum and colon during the second decade of life. "The MCC gene was discovered in 1991 through its linkage to the region showing loss of heterozygosity (LOH) in familial adenomatous polyposis (FAP)." (PMID 25200342, 2014).
hepatocellular carcinoma (2 papers, 2014 to 2024). A malignant tumor that arises from hepatocytes. "In patients with hepatocellular carcinoma, MCC regulates the oncogenic β-catenin/Wnt signaling pathway, which is often activated in such patients." (PMID 39439956, 2024). "It has been previously shown that MCC functions as a tumor suppressor gene in CRCs and hepatocellular carcinoma." (PMID 25200342, 2014). "Functional evidence and signaling pathway studies indicate that MCC acts as a tumor suppressor gene by inhibiting the oncogenic NF-κB and β-catenin pathways in CRCs and hepatocellular carcinoma." (PMID 25200342, 2014). "MCC appears to specifically target and negatively regulate the oncogenic NF-κB and β-catenin pathways in CRCs and hepatocellular carcinoma." (PMID 25200342, 2014).
liver cancer (2 papers, 2022 to 2024). An epithelial or non-epithelial malignant neoplasm that arises from the liver. "Moreover, LINE-1 retrotransposon insertion in germline DNA and a lack of MCC protein expression in normal tissue have been reported in a subset of liver cancer patients." (PMID 35740525, 2022).
lymphoma (2 papers, 2014 to 2016). A malignant (clonal) proliferation of B- lymphocytes or T- lymphocytes which involves the lymph nodes, bone marrow and/or extranodal sites. "However, the functional roles of MCC in lymphocytes or lymphomas remain unknown." (PMID 25200342, 2014). "However, expression of MCC was not reported in lymphocytes, and the function of MCC in lymphocytes or lymphomas has not been explored." (PMID 25200342, 2014).
schizophrenia (2 papers, 2015 to 2016). A major psychotic disorder characterized by abnormalities in the perception or expression of reality. "Our findings provide a unique perspective on genetic protection against CRC in patients with schizophrenia which might involve the MCC gene." (PMID 27226254, 2016). "We therefore studied the ASE at the MCC locus among CRC patients, schizophrenia patients, and normal controls, using the MassArray technique which is based on the highly sensitive and accurate MALDI-TOF-Mass Spectrometry." (PMID 27226254, 2016). "No significant discrepancy was observed in MCC gene expression among brain tissue, colon tissue and peripheral blood, thus ensuring the feasibility of performing ASE detection with the blood samples of schizophrenia cases and normal controls." (PMID 27226254, 2016).
acute myeloid leukemia (1 paper, 2022). Acute myeloid leukemia (AML) is a group of neoplasms arising from precursor cells committed to the myeloid cell-line differentiation. "Several single nucleotide polymorphisms (SNPs) within the MCC gene correlate with sensitivity to the cytotoxic drug cytarabine in acute myeloid leukemia patients." (PMID 35740525, 2022).
autism spectrum disorder (1 paper, 2015). A spectrum of developmental disorders that includes autism, and Asperger syndrome. "Remarkably, another recent study identified MCC as a potential candidate gene for autism spectrum disorders." (PMID 25997006, 2015). "However, a recent study identified MCC as a potential candidate gene for autism spectrum disorders." (PMID 25997006, 2015).
biotin deficiency (1 paper, 2023). "It is known that biotin deficiency can cause malfunction of multiple carboxylases (MCC, ACC, PCC, PC), and thereby impede the process of reactions catalyzed by these enzymes, resulting in toxicity related to accumulated substrates, and eventually, various clinical manifestations." (PMID 37373384, 2023).
brain cancer (1 paper, 2024). A primary or metastatic malignant neoplasm affecting the brain. "MCC expression levels were investigated across various cell lines, including glioblastoma and non-brain cancer cell lines, such as HaCaT and SH-SY5Y." (PMID 39439956, 2024).
brain tumors (1 paper, 2024). "Our findings regarding the aberrant subcellular location of MCC in glioblastoma suggest that MCC function and signaling are abnormal in brain tumors compared with normal tissues." (PMID 39439956, 2024).